MTOR (mechanistic target of rapamycin kinase)
Diseases named in the same sentence as MTOR in open-access papers (continued):
Sharing a sentence is not in itself a finding about the gene and the disease.
cancer (continued). "Overactivation of PI3K/Akt/mTOR is linked with carcinogenesis and serves a potential molecular therapeutic target in treatment of various cancers." (PMID 27097161, 2016). "First, although we collected all published clinical evidence investigating mTOR SNPs and cancer risk, the pooled sample size of this meta-analysis was still relatively small, especially for rs1034528, rs17036508, rs1064261, and rs3806317." (PMID 27462867, 2016). "PI3K/Akt and associated mTOR pathways are responsible for cell survival, growth, metastasis and both chemo- and radio-resistances in prostate cancer and other cancers." (PMID 27769069, 2016). "Regulatory genes for the mTOR pathway are lost or mutated in many cancers, leading to enhanced activation of mTOR and increased cell resistance to apoptosis." (PMID 27807479, 2016). "In the context of cancer, overactivation of mTORC1 is frequently observed in human tumors caused either by activating mutations of upstream components of the mTOR signaling pathway or by mutations of mTOR itself." (PMID 27153561, 2016). "We recently reported that IKKα associates with mTORC1 in PTEN-deficient cancer cells in an Akt-dependent manner to regulate mTOR kinase activity directed to S6K and 4E-BP1." (PMID 27027448, 2016). "We and others reported that aberrations of PI3K/Akt/mTOR pathway have been linked to various types of human cancer, including OSCC." (PMID 26934445, 2016). "The mTOR pathway, which is often hyperactivated in cancer cells, is implicated in the carcinogenesis and progression of CCA." (PMID 27863431, 2016). "As clinical research revealed, the EGFR or PTEN mutation would lead to continuous activation of PI3K/Akt/mTOR signaling pathway, thereby contributing to the tumorigenesis and cancer therapy resistance." (PMID 26967052, 2016). "Studies have shown that the interconnections between cancer-associated PI3K/Akt/mTOR pathway and SREBP-mediated metabolic signaling network contribute to a number of critical cellular functions." (PMID 26883200, 2016). "Recently, activating mutations of mTOR itself have been identified through mining of human cancer genome databases." (PMID 27920721, 2016). "The circRNAs (n = 142) unique to TN tumor samples were linked to a total of 370 genes of which 220 genes (p-value = 7.79E-06–1.26E-02) were associated with cancer pathways such as tight junction, antigen presentation, and mTOR signaling pathways." (PMID 27829232, 2016). "Exceptional responses to Everolimus were reported in a few patients whose cancers harbor rare activating mutations in mTOR or loss of function mutations in its negative regulators TSC1/2." (PMID 27351224, 2016). "Aberrant activation of RAS/RAF/MEK/ERK and PI3K/AKT/mTOR pathways underlies the hall marks of cancer such as increased cell proliferation, cell motility, angiogenesis, and resistance to apoptosis." (PMID 27351224, 2016). "The experimental validation that MLL2 loss-of-function increases the sensitivity of cancer cell lines to mTOR inhibition lends further support to the validity of our approach." (PMID 27095575, 2016). "Activation of the mTOR signalling pathway has recently been found to be strongly implicated in several human cancers and in age-related disease." (PMID 26097872, 2015). "mTOR was added to the list as a result of loss-of-function RNAi experiments coupled with in vitro biochemistry in Drosophila and in human cancer cells." (PMID 26536660, 2015). "In summary, PIK3CA mutations can initiate pancreatic tumorigenesis and these cancers are particularly sensitive to dual PI3K/mTOR inhibition." (PMID 26436951, 2015). "The discovery of high frequencies of mutations in the PI3K/AKT/mTOR pathway in different cancer entities has sparked interest to inhibit elements of this pathway." (PMID 26056603, 2015).
cancer (continued). "Aberrations of multiple elements of the mTOR pathway and their association with tumor progression have been extensively investigated in many types of cancers, making mTOR an appealing therapeutic target for cancer treatment." (PMID 25909163, 2015). "The most invoked mechanism underlying the cell-autonomous effect of metformin on cancer cells implies the ability to inhibit the mTOR pathway via the activation of AMPK." (PMID 26291325, 2015). "mTOR (p = 0.003) and p-mTOR (p = 0.02) staining was associated with stage of disease, with lower staining scores in the tumor center of advanced stage cancers (T3 and T4) compared to early disease (T1 and T2)." (PMID 26652716, 2015). "Mutations in RHEB are uncommon in many cancers, despite its central role in regulating downstream mTOR activation." (PMID 26255626, 2015). "Mechanistic target of rapamycin (mTOR) is a kinase found in a complex (mTORC1) that enables macromolecular synthesis and cell growth and is implicated in cancer etiology." (PMID 26158292, 2015). "Recent deep sequencing efforts have identified point mutations in MTOR in various cancers, though it remains to be assessed if these are driver mutations causally implicated in oncogenesis." (PMID 26255626, 2015). "The mTOR signaling pathway drives many major cellular processes and is implicated in an increasing number of pathological conditions including cancer." (PMID 26061184, 2015). "Using publicly available databases of cancer genome sequence data, we examined a cluster of mutations in MTOR specific to RCC located in the FAT domain of mTOR and a point mutation in the RHEB gene." (PMID 26255626, 2015). "mTOR is linked to the proliferation of cancer cells and can control the transcription of key enzymes that promote aerobic glycolysis." (PMID 25807077, 2015). "For example, in contrast with other cancers, our study indicated that mTOR rs2295080 variant genotypes (GT/GG) were associated with an increased ESCC risk, and the association became significant among subjects with BMI<25.0." (PMID 25654238, 2015). "This is supported also by pharmacological evidence that mTOR inhibition can be bypassed by RAS mutations in cancer cells." (PMID 26383020, 2015). "Recent studies have indicated that inhibition of mTOR/S6K pathway is associated with the triggering of autophagy in cancer cells." (PMID 26134510, 2015). "Novel therapeutic strategies focused on klotho, progerin and mTOR signalling have the potential to both enhance longevity and repress cancer associated with old age." (PMID 25388238, 2015). "Autophagic death was also associated with the suppression of PI3K/Akt/mTOR signaling pathway as well as a reduction in the total levels of IP3 receptor in BT-474 cancer cells." (PMID 25580621, 2015). "The phosphatidylinositol 3-kinase/Akt/mammalian target of rapamycin (PI3K/Akt/mTOR) pathway deregulation is a common event in human cancer and associated with the tumor cell proliferation, growth and apoptosis." (PMID 26130968, 2015). "First, it is clear that there is a striking correlation between inactivating mutations in TSC1 or TSC2, and activating mutations in MTOR, and response to rapalog therapy in several cancer types." (PMID 26137524, 2015). "Overexpression of mTOR or p70S6K1 has been found in many human cancers and is associated with tumor malignancy and poor prognosis." (PMID 26238185, 2015). "One challenge of rapalog basket trials is that the list of cancer genes and mutations that lead to sensitivity to mTOR inhibitors is incomplete and still evolving." (PMID 26137524, 2015). "Overall, a number of elements of the PI3K/AKT/mTOR pathway are frequently mutated in cancer, thus stimulating strong interest for PI3K-specific drug development." (PMID 26056603, 2015). "Taken together, these studies provide a rationale for the clinical application of PI3K/mTOR inhibitors as a molecular targeted approach for treating HPV-associated cancers." (PMID 26022660, 2015).
cancer (continued). "Chemicals that inhibit mTOR activity via AMPK activation or AKT inhibition have been associated with the induction of autophagy in cancer cells." (PMID 26334320, 2015). "As with other cancers, some of these mutations clustered in key regulatory domains of mTOR such as the kinase domain and the FRB (FKBP12 rapamycin binding) domains." (PMID 26255626, 2015). "The mechanistic target of rapamycin, (mTOR) kinase plays a pivotal role in controlling critical cellular growth and survival pathways, and its aberrant induction is implicated in cancer pathogenesis." (PMID 25849580, 2015). "The mTOR signaling pathway is a critical regulator of growth and cellular proliferation, and mutations that activate mTORC1 are linked to cancer." (PMID 26378060, 2015). "In most of sporadic cancers, mTOR activation is the result of activating mutation of PI3KCA, or deletion or loss-function of upstream regulator genes encoding TSC1/2 (tuberous sclerosis complex 1/2), LKB1 (liver kinase B1), or PTEN." (PMID 26357655, 2015). "PI3K/Akt-mTOR pathway, one of the most upregulated pathway observed in ovarian and other cancers, is also the common downstream pathway implicated in growth factor signaling and CR." (PMID 25895126, 2015). "Deregulation of the mTOR signaling pathway has been associated with the pathogenesis of various human cancers, and studies have shown its role in angiogenesis, progression, and treatment resistance." (PMID 26397134, 2015). "Aside from its association with cancer, deregulation of the mTOR pathway is in fact linked to several other diseases, including ocular, fibrotic, viral, skin and central nervous system diseases." (PMID 24393708, 2014). "Activation of the AKT/mTOR signaling pathway through mutation of pathway components as well as through activation of upstream signaling molecules occurs in a majority of cancers and contributes to deregulation of proliferation and resistance to apoptosis." (PMID 25098767, 2014). "In human, this pathway is frequently activated in many human diseases, including cancers, furthermore, and uncontrolled mTOR signaling had been reported to be associated with poor clinical outcome in lung, cervical, ovarian and esophageal cancers." (PMID 24816861, 2014). "Control of protein synthesis is commonly dysregulated in cancer, most frequently by mutational activation of the phosphoinositide 3-kinase, protein kinase B/Akt/mammalian target of rapamycin (PI3K/Akt/mTOR) pathway." (PMID 24970821, 2014). "In fact rapamycin (or similar mTOR inhibitors) has gained interest for the treatment of cancers, including EBV-associated post-transplant lymphoproliferative disease." (PMID 24917448, 2014). "The PTEN gene encodes a negative regulator of the PI3K/Akt/mTOR pathway and is one of the most frequently mutated genes in cancer, with loss of heterozygosity at the PTEN locus being reported in about 40% of invasive BC." (PMID 24498881, 2014). "Dysregulation of the mTOR signaling pathway is known to be implicated in various types of cancer including GBM." (PMID 24498019, 2014). "Third, what we find is also biologically plausible as causality with the fact that metformin is found to reduce cancer cell proliferation, inhibit mTOR and protein synthesis and lead to cell cycle arrest." (PMID 24647047, 2014). "In humans, deregulated mTOR (the mammalian TOR) signaling is associated with cancer and metabolic diseases." (PMID 24481314, 2014). "Because hyperactive mTOR is often found in cancer associated with activating mutation in the PI3K/AKT signaling pathway, significant effort has been made to develop therapeutic strategies that target PI3K/AKT signaling for the treatment of cancer." (PMID 25436981, 2014).
cancer (continued). "The over-activation of the mTOR signaling pathway has been implicated in many types of cancer, tissue hypertrophy, and other diseases." (PMID 24578415, 2014). "As previously demonstrated, the inhibition of the Akt/mTOR pathway is consistently associated with triggering autophagy in cancer cells." (PMID 24676456, 2014). "In this study, we found that OA reduces the expression level of phosphorylated mTOR in cancer cells associated with its inhibitory activity on aerobic glycolysis." (PMID 24626155, 2014). "Genetic alteration targeting the PI3K/Akt/mTOR pathway has been strongly implicated in cancer development." (PMID 25334061, 2014). "As with both Hsp90 and Hsf1, mTOR is often overactivated in cancer; certain gain of function mutations in the mTOR kinase domain being tumorigenic in animal models." (PMID 24970820, 2014). "A link between the mTOR pathway and endometrioid endometrial cancer is clearly evident and most of its upstream and downstream regulators are directly implicated in cancer initiation and progression." (PMID 24526917, 2014). "Loss of PTEN activates the PI3K/Akt/mTOR pathway and is associated with both resistance to chemotherapy and reduced survival in human cancers." (PMID 25334061, 2014). "The significance of translational control in cancer progression has come under recent scrutiny since several oncogenic signalling pathways, including the Bcr-Abl pathway and one of its targets, mTOR, have been linked to misregulation of translation." (PMID 25392452, 2014). "For estimating the influence of mTOR polymorphisms (rs2295080 and rs11121704) on clinical outcomes in cancer patients, 4 eligible studies included 1594 cancer patients, were identified: 2 were conducted in USA and two were in China." (PMID 24816861, 2014). "Although the mTor pathway has been linked to autophagy and cell death in the bulk of cancer cells, its involvement in cancer stem cell survival is unclear." (PMID 24682219, 2014). "Paradoxically, AMPK has been considered a tumor suppressor, while active mTOR has been associated with tumor progression in certain cancers." (PMID 25209360, 2014). "Suppression of mTOR through AMPK activation is believed to constitute the major mechanism underlying its anti-cancer activities." (PMID 24465408, 2014). "The aim of this study is to systematically evaluate the association between mTOR polymorphisms (rs2295080, rs2536 and rs11121704) and cancer risk as well as clinical outcome by a meta-analysis." (PMID 24816861, 2014). "mTOR activity is implicated as a mechanism of resistance to growth factor receptor inhibition in several cancers." (PMID 25344862, 2014). "Previously we found that the BRCA1-AKT1 pathway contributes to tumorigenesis and that the AKT1/mTOR is a novel therapeutic target for BRCA1-deficient cancers." (PMID 24831086, 2014). "Based on genotyping data available, we noticed that there was a wide variation in the T allele frequency of mTOR rs2295080 polymorphism among cancer patients between Caucasians and Asians (Chinese and Korean),ranging from 0.311 to 0.808." (PMID 24816861, 2014). "Constitutively activated PI3K/Akt/mTOR signaling as a consequence of PIK3CA mutations or PTEN loss is one of the most common lesion in human cancers." (PMID 25250015, 2014). "Disordered mTOR activity has been reported to be associated with some malignant and resistant cancers." (PMID 25153728, 2014). "The best-studied downstream substrate of AKT and one of the most commonly mutated pathways in cancer is the serine/threonine kinase mTOR (mammalian target of rapamycin)." (PMID 24829804, 2014). "Recurrent oncogenic mutations in exon 10 and 21 of PI3KCA and exon 2 of AKT, which are known to cause activation of the PI3K/Akt/mTOR pathway in several cancer types, were also excluded by sequence analysis." (PMID 24498881, 2014).
cancer (continued). "Early withdrawal of CsA and a switch to mTOR inhibitors, such as rapamycin and everolimus, have been shown to reduce the risk of cancer in renal transplant patients." (PMID 24348843, 2014). "In this meta-analysis, we focused on the common polymorphisms in mTOR gene and evaluated their correlation with cancer risk and clinical outcomed in cancer patients." (PMID 24816861, 2014). "Although mTOR is frequently activated in human cancers, mutation of the mTOR gene has been found only occasionally." (PMID 24393708, 2014). "If glucose regulation is impaired, abnormality of some growth factors pathways, for example, IGF-1, will result in improper activation of mTOR and/or inactivation of mTOR inhibitors, causing various pathologies, including cancer." (PMID 25069390, 2014). "Phosphatase and tensin homolog deleted on chromosome 10 (PTEN) is a tumor suppressor protein that negatively regulates the PI3K/AKT/mTOR signaling pathway and has been found to be mutated in many different cancers." (PMID 24887156, 2014). "Intriguingly, only metformin, which affects the mTOR pathway, has been reported to not only reduce not only the risk of cancer, but of other age-related diseases as well." (PMID 25361007, 2014). "Intriguingly, the mTOR pathways along with Hh (and other) pathways have been implicated in the maintenance of cancer stem cells (CSCs)." (PMID 24859412, 2014). "DAVID ontology analysis revealed enrichment of cancer-associated pathways, including the well-characterized cancer genes MTOR, EGFR, AKT1, and CASP8 in the region of overlap." (PMID 25294808, 2014). "The similarity of the kinase domains between mTOR and PI3Ks and the importance of PI3K signaling dependent of mTOR can cause ATP-competitive PI3K/mTOR kinase inhibitors to serve a key function in targeted cancer treatment." (PMID 25610711, 2014). "In line with these essential cellular functions, mTOR dysfunction is associated with a broad range of human diseases including cancer, type II diabetes and obesity, and major efforts to develop drugs targeting the pathway are underway." (PMID 24574959, 2014). "Through the primary literature research in Pubmed, 61 studies were identified for cancer risk and/or clinical outcome assessment for mTOR polymorphisms." (PMID 24816861, 2014). "Cancer stem cells are able to escape this process through secondary mutations that attenuate mTOR-dependent tumor suppressive mechanisms." (PMID 24757526, 2014). "Recent studies indicate that other pathways, in addition to the PI3K/Akt/mTOR pathway, can cause translational dysregulation in cancer." (PMID 24970821, 2014). "Together with the phosphatidylinositol-3-kinase (PI3K)-AKT transduction pathway, mTOR forms a signaling network that has been implicated in various types of cancer." (PMID 23829943, 2013). "One possible explanation for this is that mutations in the components of the mTOR pathway, which have been identified in many cancers and cancer cell lines, mask the effect of metformin in EpCAM+ Huh1 cells." (PMID 23922888, 2013). "This has profound implications as mTOR activity is important in many cancers and is downstream of important tumor suppressors and oncogenes that are frequently mutated in human cancers." (PMID 23476113, 2013). "A total of 29 genes were associated with cancers, and 12 were associated with hematological disease, including the MTOR gene which is in the Akt/mTOR pathway and is critical for cell survival and proliferation in high-risk MDS patients." (PMID 24244432, 2013). "But until now, several studies have identified the effect of this polymorphism in mTOR for cancer risk, all of which considered rs2295080 T allele as a risk factor." (PMID 23555892, 2013).